IL6 (interleukin 6)
Diseases named in the same sentence as IL6 in open-access papers (continued):
Sharing a sentence is not in itself a finding about the gene and the disease.
tumor (continued). "By reducing IL-6 in hypoxia, the ethanolic extract of Brazilian propolis (EEP-B) may weaken the IL-6→STAT3→HIF-1α loop, thereby dampening pro-inflammatory and pro-angiogenic signaling within the TME, which could potentially limit tumor progression." (PMID 41302515, 2025). "Further, LINC02268 could activate the interleukin-6 (IL6)/janus kinase (JAK)/signal transducer and activator of transcription 3 (STAT3) signaling pathway, crucial for driving tumor advancement and metastasis in the tumor microenvironment." (PMID 40538623, 2025). "Activation of IL-6/STAT3 impairs dendritic cell antigen presentation, reduces T cell responses, and promotes the accumulation of immunosuppressive cell populations such as regulatory T cells and myeloid-derived suppressor cells, fostering an immunosuppressive tumor microenvironment." (PMID 41409248, 2025). "Elevated levels of specific pro-inflammatory cytokines, such as IL-1, IL-6, IL-8, and TNF-α contribute to tumor progression and invasion by promoting cell proliferation, epithelial–mesenchymal transition (EMT), and vascularization, while also enhancing the tumor’s ability to evade immune detection." (PMID 41007256, 2025). "IL-6 is a component of the tumor microenvironment (TME), which represents all the non-cancerous host cells in the tumor, such as fibroblasts, endothelial cells and immune cells, along with non-cellular components, including extracellular matrix (ECM), cytokines and growth factors." (PMID 41303164, 2025). "Consistent with the results obtained from in vitro assays, IHC staining disclosed a significantly suppressed expression of senescence marker P21 and SASP cytokines like IL6 and IL1β in tumor samples, regardless of GDC-0879 mono- or combined therapy with anti-PD1." (PMID 40781221, 2025). "While the interaction between tumor-associated SCs and NK cells has not yet been documented, SC-derived TGF-β, PgE2, IL-6, and other molecules are known to control the activation and function of NK cells, suggesting a likely crosstalk between SCs and NK cells in the tumor environment." (PMID 40940747, 2025). "TAMs, fibroblasts within the tumor stroma, Trges, and MDSCs are present in TME, and molecules contributing to immunosuppression and the increased expression and activation of TGF-β, IL-10, IL-6, IL-8, prostaglandin E2, VEGF, PD-1, and PD-L1 are secreted by these cells." (PMID 40563393, 2025). "Additionally, IL-6 signaling interacts with other pro-proliferative pathways, such as PI3K/Akt and MAPK/ERK, therefore enhancing their effects and providing a cellular milieu favorable for tumor growth and survival." (PMID 40868199, 2025). "Elevated levels of pro-inflammatory cytokines such as interleukin-6 (IL-6) and tumor necrosis factor-alpha (TNF-α) promote survival pathways, chemoresistance, and immune evasion, while anti-inflammatory cytokines like IL-10 further suppress effective anti-tumor immunity." (PMID 40486628, 2025). "Thus, IL-6 is not required for primary tumour growth or for early cancer-cell dissemination to the lungs." (PMID 40739350, 2025). "Particularly, intravesical instillation of VB-85247 induced elevated gene expression in the tumor-bearing bladders for IFNβ, CXCL10, CCL5, IL6, and TNFα at 4 hours after treatment, with the fold-induction of gene expression in the order of IFNβ > CXCL10 > CCL5 > IL6 > TNFα." (PMID 39700406, 2025). "Similarly, targeting the secretion of pro-inflammatory cytokines like TNF-α or IL-6 from adipocytes may alleviate inflammation within the TME and enhance anti-tumor immune responses." (PMID 41200178, 2025).
tumor (continued). "This indicates that IL-6 may promote the expression of PCNA, MMP-9, VEGF, and others following RFA treatment, thereby enhancing proliferation, invasion, and angiogenesis, highlighting its central role in tumor progression." (PMID 41403696, 2025). "However, there is a line of evidence concerning the antitumor effects of IL-6, which is produced by stromal cells and plays a key role in the hyperthermia-mediated increased trafficking of lymphocytes, such as CD8+ CTLs, across the tumor vasculature." (PMID 41375025, 2025). "Key mechanisms include: Oxidative Stress, Pro-inflammatory cytokines such as interleukin-6 (IL-6) and tumor necrosis factor-alpha and angiogenesis and tissue remodeling like vascular endothelial growth factor (VEGF) stimulate new blood vessel formation, supporting tumor growth and metastasis." (PMID 41386876, 2025). "Additionally, FABP5 is closely associated with tumor-related signaling pathways, such as PPAR-γ, NF-κB, and IL-6/STAT3, and may promote tumor progression and metastasis through these pathways." (PMID 40717587, 2025). "Immunosuppressive cells within the tumor microenvironment disrupt T cell activation and proliferation by increasing the expression of immunosuppressive receptors such as PD-1 and CTLA-4 and by releasing immunosuppressive cytokines like IL-6, IL-10, TGFβ, and VEGF." (PMID 40625850, 2025). "In the early stages, SASP components such as IL-6, IL-8, and CCL2 recruit immune cells to eliminate damaged cells, but prolonged SASP signaling alters this equilibrium, driving chronic inflammation, suppression of immune responses, and ECM remodeling, thereby facilitating tumor development." (PMID 41463272, 2025). "Similarly, combining IL6 with HE4, another biomarker that detects OC recurrence, may improve OC screening or facilitate early tumor detection." (PMID 40427188, 2025). "Finally, there were no significant changes in the levels of IL‐6 cytokine in the prefrontal cortex of either stressed or tumour‐bearing mice." (PMID 40172096, 2025). "Interestingly, TGFB3 and IL6 exhibited a strong correlation in tumor tissues but not normal tissues." (PMID 40650134, 2025). "Similarly, decreased expression levels of miR-143-3p in E vs. C could contribute to overexpression of IL-6, HIF-1α and NF-κB p65, as observed in tumor growth." (PMID 41013698, 2025). "Understanding how the combined treatment of PDT and CAP affects cytokine mRNA expression levels such as IL-6 and IL-8 in SCC may help to optimize treatment protocols and improve therapeutic outcomes by balancing anti-tumor effects with potential inflammatory responses." (PMID 40573301, 2025). "Regarding the cytokine profile, notable modulations were observed in the levels of IL-1β, IL-4, IL-6, IL-10, IL-17A, and TNF-α, particularly in the FMT groups, indicating an influence on the local immune response that could contribute to shaping the tumor microenvironment." (PMID 41614846, 2025). "Additionally, L-RES downregulated CAF activation markers α-SMA and IL-6, inhibited CAF-induced cancer cell invasion (Boyden chamber and spheroid invasion assays), and was more effective than free resveratrol in suppressing tumor–stroma interactions." (PMID 40572668, 2025). "Furthermore, IL-6 increases the expression of adhesion molecules, such as ICAM-1, VCAM-1 and E-selectin on endothelial cells, as well as L-selectin on lymphocytes, which results in increased transmigration of leukocytes into the tumor area." (PMID 41009634, 2025). "As no increase in IL-6 levels was observed in the static group in this study, the increase in IL-6 levels may not be due to the impact of the tumor." (PMID 40281902, 2025). "Macrophages also migrate to the tumor site, where tumor cells are responsible for a switch in macrophage phenotype, favoring a pro-invasive and immunosuppressive M2 state via the release of immunosuppressive factors, such as CSF-1, CCL2, IL-4, IL-6, IL-10, and TGF-β." (PMID 41373591, 2025).
tumor (continued). "In cancer patients, the tumor itself, treatment side effects, and psychological stress can all serve as chronic stressors, continuously activating the innate immune system and HPA axis, leading to elevated levels of pro-inflammatory cytokines (such as TNF - α, IL-6) and cortisol." (PMID 41480347, 2025). "Additionally, clinical chemistry data of secreted proteins showed that tumor‐border slices, but not non‐tumor slices, produced known tumor‐associated markers, including CA15‐3, CA19‐9, CA72‐4, CA125, CEA, S100, ferritin, and IL‐6." (PMID 40952312, 2025). "In other words, when combined with ICI therapy, IL-6 antagonists may provide a synergistic anti-tumor effect in cancer patients without worsening toxicity." (PMID 41019062, 2025). "The augmented presence of immune ligand-receptor pairs such as IL-6, TNFSF13B, LGALS9-CD45, and HLA-E-KIR underscores the pivotal role of macrophages in modulating inflammatory responses, immune evasion, and reshaping the tumor microenvironment within the context of elevated LST1 expression." (PMID 41488617, 2025). "Given that elevated levels of IL-6 are induced post-RFA treatment, surviving tumor cells at the periphery of the ablation zone may be inadvertently stimulated to proliferate by circulating IL-6, potentially leading to tumor recurrence and rapid progression." (PMID 41403696, 2025). "Furthermore, IL-6 released in the tumor microenvironment suppresses the differentiation of IFN-γ-producing TH cells by reducing MHC-II surface expression and IL-12 secretion in dendritic cells of tumor-bearing mice." (PMID 39652104, 2025). "Given the tumor-promoting role of CD109 and of IL-6 in SCC and the recent findings that CD109 potentiates JAK/STAT3 signaling in lung adenocarcinoma and glioblastoma cells, it was important to establish whether CD109 regulates IL6Rα signaling in SCC and determine the mechanisms involved." (PMID 40317079, 2025). "In the context of PMN formation, IL-6 can elicit both direct intrinsic effects on cancer cells, such as cell-cycle progression, invasion, and metastasis, and indirect, cell-extrinsic effects on the TME, including the promotion of angiogenesis, tumor-promoting inflammation, and immune suppression." (PMID 40099972, 2025). "Particularly, M1-type TAMs secrete a repertoire of pro-inflammatory cytokines including IL-1β, IL-6, and tumor necrosis factor-alpha (TNF-α), alongside generating ROS that potentially inflict DNA damage, thus catalyzing innate immune responses conducive to the obliteration of tumor cells." (PMID 40664640, 2025). "This negative modulation may result in decreased IL-6 expression, which directly impacts the balance of the tumor microenvironment, as IL-6 plays an essential role in immune regulation and tumor cell behavior." (PMID 40733498, 2025). "To examine whether tumor growth may be altered by these opposing immune-modulating effects in vivo, we evaluated the impact of PTIS blockade indirectly by disrupting IFN-regulation or directly by blocking one secretory factor, such as IL6." (PMID 39663510, 2025). "Chemotherapeutic drugs may change fibroblasts into a CAF-like senescent phenotype that produces protumor inflammatory cytokines, such as interferons and IL-6, even when no surrounding tumor cells exist." (PMID 40584290, 2025). "Similarly, IL-6-driven lactate production upregulates PD-L1 expression on uveal melanoma cells through activation of the GPR81-cAMP-PKA signaling cascade, thereby promoting immune evasion and facilitating tumor progression." (PMID 41152975, 2025). "Irradiated tumor cell–derived exosomes display strong immunogenic activity, inducing IFN-related genes (IFN-β, Mx1, IFNAR1) in DCs and stimulating the release of IFN-β, IL-6, and CXCL10, which together promote an inflammatory niche that supports T cell priming." (PMID 41204180, 2025). "Furthermore, VEGF, IL‐6, and CXCL5 stimulate angiogenesis to support tumor metastasis." (PMID 39811803, 2025).
tumor (continued). "Considering the established roles of Interleukin (IL)-6 and IL-17A in non-small cell lung cancer (NSCLC) progression and immune evasion, we developed a combination strategy integrating cytokine neutralization with CTT (combination therapy) in LLC1 tumor-bearing mice." (PMID 41084279, 2025). "It has been widely documented that IL-6 mediated activation of STAT3 signaling further triggers the transcription of various downstream target genes, including MMPs, Cyclin family members, and EMT makers, enhancing tumor cell survival, proliferation and invasion." (PMID 40055805, 2025). "Along with the predictive determinants of tumor burden (MC), biological tumor aggressiveness (AFP level, 18F-FDG avidity) and systemic inflammatory state (IL-6 level), CEPH could be identified as another significant and independent predictive factor in our multivariable analysis." (PMID 40142840, 2025). "Additionally, HMGB1 induces CAF secretion of pro‐tumor factors (IL‐6, TGF‐β, VEGF) through a RAGE‐dependent mechanism, promoting tumor angiogenesis, immunosuppressive cell (Treg, MDSC) recruitment, and ECM remodeling—to build a stromal barrier favorable for tumor growth/metastasis." (PMID 41354099, 2025). "Furthermore, we present existing and new treatment methods that are centered on CAFs, such as suppression of the paracrine pathway (e.g., IL-6/STAT3, TGF-β), depletion of CAFs lineages by targeting fibroblast activation protein (FAP), and conversion toward tumor-restraining CAFs." (PMID 40959080, 2025). "Next, we evaluated whether these alterations were IL-6-specific or indirect outcomes of the lack of IL-6 signaling in the tumor." (PMID 39653766, 2025). "However, pro-inflammatory dietary components like saturated fats may counteract these benefits by activating NF-κB signaling, which upregulates angiogenic cytokines (e.g., IL-6, TNF-α) to fuel tumor progression." (PMID 40236640, 2025). "They express the CCR2, CCR5, and CXCR2 chemokine receptors, which are then mobilized to the blood and tumor by chemokine ligands (CCL2, CCL5, CXCL1-8) and other inflammatory mediators like prostaglandin E2 (PGE2) generated by TME, VEGF, TGF-β, TNF-α, and IL-1β, IL-6, and IL-10." (PMID 40727443, 2025). "Additionally, sarcopenic patients often exhibit chronic inflammatory states, such as elevated IL-6 and TNF-α levels, which may promote tumor progression and suppress immune response." (PMID 41459515, 2025). "Additionally, M2d-polarized macrophages stimulated by adenosine, IL-6 and tumor cells secrete proteases (such as MMP-2), cytokines (such as VEGF) and anti-inflammatory factors (such as TGF-β and IL-10) to promote angiogenesis and tumor immunosuppression." (PMID 40703527, 2025). "To the best of our knowledge, we are the first to show a tumor-promoting paracrine loop in which DDLPS cells release microRNAs 25-3p and 92a-3p in extracellular vesicles which then interact with toll-like receptors 7 and 8 in macrophages, inducing elevated IL6 secretion." (PMID 40961077, 2025). "This case suggests that residual IL-6 suppression from prior tocilizumab therapy may attenuate the severity of subsequent irAEs, permitting effective management without compromising anti-tumor efficacy." (PMID 41244903, 2025). "Additionally, transient increases in inflammatory cytokines such as IL-6 and IL-1β following DSS administration have been reported, and these cytokines are known to promote tumor cell proliferation, immune evasion, and defective DNA repair, thereby facilitating tumorigenesis." (PMID 41285904, 2025).
tumor (continued). "Because IL-6 and IL-8 potentiate each other's biological effects and alter the activity of steroidogenesis enzymes, they can have a direct or indirect impact on the expression of estrogen, progesterone, and HER2 receptors by tumor cells in IBC NST of the luminal B HER2-positive subtype." (PMID 40584290, 2025). "Additionally, they interfere with the IL-6/STAT3 axis, a key driver of chronic inflammation-induced tumorigenesis, thereby reducing pro-survival and pro-inflammatory gene expression that promotes tumor progression." (PMID 41515306, 2025). "MMW irradiation also induced tumor cells to secrete higher levels of immune-activating factors, such as tumor necrosis factor-α (TNF-α), interleukin-6 (IL-6), and interleukin-12 (IL-12), which could enhance the immune response of the body and thus clear the residual tumor more effectively." (PMID 41383334, 2025). "Interactions between CAF, tumor, and mesenchymal cells take place with the participation of exosomes, and the stimulants are transforming growth factor beta (TGF-β), fibroblast growth factor (FGF), platelet-derived growth factor (PDGF), interleukin-1 (IL-1), and interleukin-6 (IL-6)." (PMID 39561105, 2025). "In addition, IL-6-induced STAT-3 activation occurs in tumour-infiltrating immune cells, where it exerts a negative regulatory effect on neutrophils, natural killer (NK) cells, and effector T cells, contributing to an immunosuppressive tumour microenvironment." (PMID 39858001, 2025). "Alongside TNF-α, IL-6 contributes significantly to amplifying NF-κB-driven inflammation by activating the JAK/STAT3 pathway, which can subsequently boost NF-κB signaling This establishes another positive feedback loop that sustains chronic inflammation and supports tumor growth." (PMID 39949765, 2025). "JAK inhibitors may block STAT3 signaling, but they can inadvertently activate NF-κB in macrophages, leading to the secretion of pro-survival factors such as IL-6 and CSF2, which activate tumor cell STAT3 and PI3K signaling through paracrine mechanisms, forming an escape loop from treatment." (PMID 40936705, 2025). "Silibinin inhibits tumor growth through immunomodulatory activities, such as regulating immune cells (Tregs, macrophages, DCs, NK cell), inhibiting inflammatory cytokines (IFN-γ, IL-2, IL-6, IL-10, IL-12, TNF-α, and TGF-β), and modulating immune check points (PD-L1 and PD-1)." (PMID 40490812, 2025). "This lack of benefit might be attributed to tumor heterogeneity and the involvement of IL-6 in multiple complex regulatory mechanisms, requiring validation in numerous clinical trials." (PMID 40433391, 2025). "These include IL-6 blocker stuximab, IL-6R receptor blocker tolizumab, JAK inhibitor ruxolitinib, and STAT3 inhibitors, which have been shown in preclinical experiments to significantly inhibit tumor growth, increase immune cell numbers, and improve the immunosuppressive microenvironment." (PMID 40433391, 2025). "During chronic inflammation, various inflammatory factors, such as interleukin 6 (IL6), tumour necrosis factor (TNF) and interferon (IFN), are released, and immune cells, including T lymphocytes, macrophages, neutrophils, and dendritic cells, accumulate within the tumour and surrounding tissues." (PMID 40913253, 2025). "However, targeted inhibition of IL‐6 signaling may reduce STAT1 activity, which possesses tumor‐suppressive properties, presenting a potential challenge for cancer treatment." (PMID 40166646, 2025). "Pre-transplant higher serum levels of CRP and IL-6 observed in our CEPH group seem to support this hypothesis, as they may not only reflect systemic inflammation but were also shown to correlate with immune status at the tumor site." (PMID 40142840, 2025). "Furthermore, IL-6 secretion induced by platinum-based chemotherapy promotes cancer stem cell (CSC) enrichment in high-grade serous carcinoma (HGSC), facilitating CSC expansion from dormant senescent cells, a crucial driver of tumor recurrence." (PMID 40703657, 2025).